LINC02471 (long independently transcribed non-coding RNA 2471)
Synonyms: AC079630.2
Gene: Long non-coding RNA gene on chromosome 12 (40,156,109 to 40,211,419, forward strand). Ensembl gene ENSG00000223914.
Diseases named in the same sentence as LINC02471 in open-access papers:
LINC02471 is named in the same sentence as 5 diseases in open-access papers, as found by Europe PMC text mining. Sharing a sentence is not in itself a finding about the gene and the disease. The quoted sentences say what the papers report.
thyroid cancer (2 papers, 2021 to 2022). "LINC02471 has been reported as a risk factor in thyroid carcinoma." (PMID 34094983, 2021). "The expression levels of LINC02471, LINC02408, LOC642484, and ATP6V0E2-AS1 were significantly different between the malignant nodules and paired normal thyroid tissues as in TANRIC thyroid cancer dataset." (PMID 36132147, 2022).
adenoma (1 paper, 2021). A neoplasm arising from the epithelium. "The expression of LINC02555 and LINC02471 increased during the progression from adenoma to carcinomas and was significantly higher in fvPTC and clPTC than in FA." (PMID 34408227, 2021).
papillary thyroid carcinoma (1 paper, 2021). "LINC02471, a member of the intergenic lncRNA family, is recognized as a crucial enhancer in papillary thyroid carcinoma (PTC)." (PMID 34594376, 2021).
tumor (2 papers, 2021 to 2022). "The knockdown of LINC02471 increases the expression of miR-375, which would inhibit the proliferation and invasion and promote the apoptosis of tumor cells." (PMID 34094983, 2021).
LINC02471 also shares sentences with these, for which no sentence is quoted: carcinoma (1 paper).